CD24 (CD24 molecule)
Diseases named in the same sentence as CD24 in open-access papers (continued):
Sharing a sentence is not in itself a finding about the gene and the disease.
tumor (continued). "Expression of CD24 may provide an enhanced capability of tumor cells to adhere to activated endothelial cells mediated by its P-selectin binding site or alter cellular signaling." (PMID 26578846, 2015). "Studies have shown that CD24 is a ligand for P-selectin, an interaction that could be important in the dissemination of tumor cells and a key factor in recruiting lymphocytes into neoplastic tissue." (PMID 26078485, 2015). "Furthermore, CD24+ cells are driven to differentiate in response to intra-tumor stimuli into a distinct CD24− cell population, thus, creating intra-tumor heterogeneity." (PMID 26040280, 2015). "Changes in CD24 expression in cancer cell lines can alter cellular properties and tumor growth." (PMID 26394139, 2015). "Moreover, CD24+ cell tumors had an enhanced tumor growth rate compared to the CD24− cell tumors in both WT (3.8-fold) and MKR mice (2.75-fold)." (PMID 26040280, 2015). "CD24 alone, or in a panel of serologic markers, may be a very useful clinical tool in screening asymptomatic individuals for CR neoplasia and would better guide the utilization of resources for colonoscopic evaluation." (PMID 26078485, 2015). "Tumor cells were predominantly CD44+/CD24- and CD49f+/EpCAM+." (PMID 26311223, 2015). "The factors that significantly predicted poor patient survival based on univariate analysis were high CD24 expression, larger tumour size, the presence of LN metastasis, advanced pathologic stage, and higher histologic grade, but not ER or PR hormone receptor status." (PMID 26444008, 2015). "To test this possibility, we measured CD24 and CD49f to quantify putative tumor initiating cells." (PMID 25970777, 2015). "CD24 may be involved in tumor development through the promotion of tumor cell proliferation, invasion and metastatic spread." (PMID 25511546, 2015). "Tumor-initiating cells are characterized by low levels of membrane CD24 expression." (PMID 26372732, 2015). "Additionally we found significantly higher levels of Twist2 in the CD24+ cells, a transcription factor that enhances tumor invasion by promoting an epithelial-mesenchymal transition." (PMID 26040280, 2015). "CD24 expression at early stages of the cancer process is an indication of a highly invasive tumor." (PMID 26040280, 2015). "A large body of literature suggests a role for CD24 in tumorigenesis and tumor progression." (PMID 24612587, 2014). "First, CD24+/CD44+ cells may have been generated during the in vivo tumor growth from CD24-/CD44+ cell population." (PMID 24612587, 2014). "To determine whether CSCs are linked with tumor aggressiveness or malignancy, we performed flow cytometric analyses of bCSC markers CD44+/CD24-/low in patient-derived tumor samples of different stages." (PMID 25315241, 2014). "CD44+/CD24- tumor cells (CSC) from clinical specimens were sorted using flow cytometry." (PMID 24884516, 2014). "Previous studies have demonstrated that CD24 is involved in cell adhesion and metastatic tumor spread, and may be one of the cancer stem cell markers expressed in various cancer cell lines." (PMID 24612587, 2014). "The CD24 gene has raised considerable interest in tumor biology." (PMID 24612587, 2014). "However, the size of tumor generated by CD24+/CD44+ cells was significantly larger than the size of the tumors from CD24-/CD44+ or unsorted control cells indicating CD24+/CD44+ cells are highly aggressive." (PMID 24612587, 2014). "Additionally, CD24+ cells isolated from patient tumor specimens are enriched in ovarian CSC/TICs and have stem-like properties, including higher levels of chemoresistance, self-renewal and differentiation than CD24− cells." (PMID 23528891, 2013). "However, our current data also showed that CD44+/CD24+ cells formed tumor xenografts in two of six mice after the injection of 1×105 cells." (PMID 23799994, 2013).
tumor (continued). "In human carcinomas, there is evidence that CD24 expression is related to prognosis and may contribute to metastasizing tumor cells, but the relationship between CD24 and prognosis is not completely understood." (PMID 23419168, 2013). "This phenomenon may suggest that an additional marker, such as CD24, should be added for tumor-derived exosome enrichment from blood in the future." (PMID 24379986, 2013). "However, this was not reflected by a corresponding increase in the size of the CD29/CD24 tumor subpopulations as observed by FACS." (PMID 24069241, 2013). "Relapsed tumor cells show CD44+CD24- phenotype with higher rates of tumorigenesis, in vivo." (PMID 24324806, 2013). "We demonstrate that it can suppress the tumor progression genes Src and CD24." (PMID 23533633, 2013). "CD24 has recently received attention in tumor biology research, as several studies have reported that the protein is broadly overexpressed in numerous types of cancer cell from the lung, breast, prostate, liver, kidney, pancreas and ovary, as well as in lymphomas." (PMID 23946784, 2013). "Furthermore, CD24 expression positively and significantly correlated with Src gene expression in the resected tumor tissues (p = 0.001), and Src expression showed a trend towards negative association with miR-34a expression." (PMID 23533633, 2013). "Thus, we analyzed how CSE affects the distribution of specific cell surface markers that are associated with tumor initiation and self renewal, specifically ALDH1 activity, high CD44/low CD24, CD49f and CD133." (PMID 23919753, 2013). "It is possible that CD24-expressing tumor cells may disseminate more easily as a result of their enhanced ability to attach to normal endothelial cells." (PMID 23946784, 2013). "We observed that Pdcd4 and miR-34a were significantly downregulated, whereas CD24, Src, and miR-21 were significantly upregulated in the tumor tissues as compared to the respective normal tissues (p = 0.003; p = 0.05; p = 0.001; p = 0.05 and p = 0.002; respectively)." (PMID 23533633, 2013). "We have previously shown that expression of CD24 is a mechanism that can activate Src kinase activity in the tumor context, consistent with the observation that the Ras/ERK/MAPK pathway that is activated by Src is downregulated as a consequence of targeting of CD24." (PMID 23533633, 2013). "In addition, cells were analyzed by FACS for cell surface proteins which differentiate luminal versus basal/myoepithelial cells (EPCAM/CD49f) and cancer cells with tumor initiating capabilities (CD44/CD24)." (PMID 23879992, 2013). "The observed effects of CD24 on cell invasion indicate that its expression may affect tumor invasiveness by altering the expression of genes involved in metastasis." (PMID 24179538, 2013). "In addition, CD24/CD44 staining of the established tumor cell lines MCF-7 (Luminal ER+, PR+, HER2-), T47D (Luminal ER+, PR+, HER2-) and MDA-MB-231 (Basal ER-, PR-, HER2-) indicated these cells had one main population." (PMID 23879992, 2013). "Thus expression of CD24 repeatedly emerges from transcrptional profiling as being correlated with tumorigenesis and tumor progression." (PMID 23533633, 2013). "Moreover, CD24 positively correlated with the amount of Src protein in tumor tissues, and a trend towards an inverse correlation between miR-34a and Src protein levels was also observed." (PMID 23533633, 2013). "Conversely, the CD44−/CD24+ cells were usually found in the central portion of the tumours." (PMID 23028444, 2012). "Our results showed that CD24 and Lyn expression increased with tumor progression." (PMID 22731636, 2012). "Similarly with the relation with DFS, the proportion of CD44+/CD24-/low tumor cells (P = 0.001), basal-like feature (P = 0.029), and TNM stage (P = 0.027) were strongly correlated with OS." (PMID 22762532, 2012). "But how epithelial cell lines like MDA-MB-468 with high CD24 expression could induce tumours remains unclear." (PMID 22693526, 2012).
tumor (continued). "We therefore termed the CD24+/ALDH1+/CD44high cells tumor-initiating cells (TICs)." (PMID 22452810, 2012). "To separate the basal and luminal-type tumor cells, we first applied a standard method for discriminating normal basal and luminal mammary epithelial cells (cell surface expression of CD49f and CD24;), but found that, despite their molecular similarities, this protocol offered little resolution." (PMID 22347416, 2012). "CD24, a heat stable antigen, is another surface marker expressed in many tumour types." (PMID 22693526, 2012). "It was therefore postulated that the content of CD44+CD24-/low cells or, in other words, the proportion of BCSCs might be related to tumor aggressiveness and distant metastasis, but the relationship with axillary LN status was not well established." (PMID 23046710, 2012). "In a similar PyMT tumor cell transplant paradigm to ours, the population of CD24 (heat stable antigen)hi/CD29(β1-integrin)+/CD61(β3-integrin)+ cells was found to significantly increase during tumor progression, specifically at the transition from hyperplasia to carcinoma." (PMID 22225988, 2012). "Using this method, we found that CD44+/CD24− cells were typically arranged in small clusters (10–15 cells), often located at the periphery of the tumour, adjacent to the surrounding stroma, while the CD44−/CD24+ cells were usually found in the central portion of the tumour." (PMID 23028444, 2012). "It seems that few alterations may take place in regulating the level of CD24 expression on membrane surface during tumour initiation and metastasis." (PMID 22693526, 2012). "CD44+/CD24- tumor cells were detected in 70.1% of the tumors, with a median proportion of 5.8%." (PMID 22762532, 2012). "A group of 7 tumours expressed CD24 in a range of 3.3 to 16.9%." (PMID 22433494, 2012). "In addition, further work on the methylation status of the TGM-2, MMP-2 and CD24 genes in other multi-factorial human non-neoplastic diseases such as diseases involving scarring or aberrant wound healing are warranted." (PMID 21359202, 2011). "It was previously shown that cell surface molecule CD24 expressed on tumor cells can support rolling on P-selectin and thus CD24-P-selectin pathway may be an important element in recruiting tumor cells to target organs." (PMID 21714887, 2011). "In contrast to ER+ disease, the CD44+CD24-/low phenotype was associated with higher tumour grade in ER- cases with 76% of positive tumours being grade 3 compared to 66% of negative cases (P = 0.020)." (PMID 22112299, 2011). "Moreover, CD24 has been demonstrated to promote tumor cell invasiveness in animal model and in vitro." (PMID 21359202, 2011). "We further classified the cases into negative (<5% n=80) and positive (⩾5% n=12) groups for ALDH1 and found that the ALDH1-positive group contained a higher proportion of CD44+/CD24− tumour cells than the ALDH1-negative group (median (interquartile range), 45% (20–70%) vs 5% (1–30%); P=0.003)." (PMID 21559013, 2011). "Thus, mAb to membrane proteins overexpressed in tumors such as CD24 or EpCAM can be used to enrich tumor derived exosomes." (PMID 21651777, 2011). "Taken together with the differential expression of HER-2, these findings provides further evidence on the worse prognosis found in CD44+CD24-/low positive tumors, and might contribute to the more aggressive behavior of these neoplasms." (PMID 21824412, 2011). "Thus, CSCs have been identified in a variety of solid malignancies with the identification of CSCs in these tumours being based on cell surface markers such as CD24, CD44, CD133 and Sca-1." (PMID 21468047, 2011). "Prior analysis of these tumors using functional assays of tumor initiating potential have showed that the tumor-generating cells had a predominantly basal character, and they were enriched in a Thy1+/CD24+ cell sub-population (1% of total Lin− cells, showing 35× enrichment of functional activity)." (PMID 21541292, 2011).
tumor (continued). "However, neither the basal secretion of IL-6 nor the induced secretion of IL-6 by PGE2 in fibroblasts correlated with fibroblast tumor promoting ability in vivo or their ability to expand CD44+/CD24−/EpCAM+ cells in vitro." (PMID 21957456, 2011). "Also, all tumor xenografts derived from CD24+ and CD24− cells expressed CD24 on their cell surface in vivo." (PMID 21317983, 2011). "Further study may clarify the link between the CD24-Siglec G pathway and innate inflammatory response which occurs in invading tumor and facilitates to establish tumorigenesis." (PMID 20950440, 2010). "By what mechanism TGF-β-like GDF3 induces up-regulation of CD24 on tumor cells, however, remains unknown." (PMID 20950440, 2010). "Conversely, these cells may represent only a subpopulation of tumor stem cells found previously to display various combinations of CD24, CD74, and CD133." (PMID 20175927, 2010). "Recent studies have demonstrated that induction of EMT using Twist and Snail in transformed mammary epithelial cells creates populations that are highly enriched for cancer stem cells as evidenced by increased CD44+/CD24- expression, mammosphere formation and tumor seeding ability." (PMID 20615238, 2010). "Primary tumor tissues, in general, showed a different spectrum of cellular heterogeneity compared to breast reduction mammoplasty tissue by flow cytometry when stained for EpCAM, CD49f, and CD24." (PMID 20964822, 2010). "Moreover, when we transplanted both populations of 1 × 102 HCC1954-Luc, we found that tumours were generated only by the CD24−/low/CD44+ population (n=6)." (PMID 19997106, 2010). "Our results also demonstrate that there may be a potentially new subpopulation (CD24+/CD44+) of tumor initiating cells in HNSCC." (PMID 19602232, 2009). "This motivated further analysis of the prevalence of CD44+/CD24- cells in different tumor subtypes." (PMID 18559090, 2008). "We did not see any association between the CD44+/CD24- status and markers known to be important for the clinical outcome, including tumor size, nodal status or S-phase fraction." (PMID 18559090, 2008). "Interestingly, tumor cells were mostly positive for either CD44 or CD24 and rather few tumors contained double-positive cells, although it was quite common that individual tumors contained both CD44+ and CD24+ cells." (PMID 18559090, 2008). "In 12% (28/240) of the tumors, the majority (> 50%) of tumor cells was CD44+/CD24-." (PMID 18559090, 2008). "The CD44+/CD24- phenotype was clearly related to certain tumor biological characteristics." (PMID 18559090, 2008). "Moreover, while one mouse injected with CD44+CD24+ cells formed a tumour in a similar time frame as mice injected with CD44+CD24− cells, the other two mice that formed tumours had an approximately 1 month longer latency period." (PMID 18268494, 2008). "Also, note that the parental and tumor-derived variants of MDA-MB-231 and MDA-MB-436 had similar CD44+/CD24- subpopulations." (PMID 17062128, 2006). "CD24 is a ligand of P-selectin and could thus promote the dissemination of CD24-positive tumor cells." (PMID 16539730, 2006). "Most probably, CD24 facilitates intravasation of tumour cells." (PMID 16892043, 2006). "We hypothesise that the decreased survival of NSCLC patients with strongly CD24-positive tumours is related to an enhanced propensity of haematogenous metastasis formation, which might be P-Selectin mediated." (PMID 12610508, 2003). "This ubiquitous expression obviously excludes a diagnostic use of CD24 as a specific marker for NSCLC or any other tumour type." (PMID 12610508, 2003). "Importantly, in the Cox regression-based multivariate analysis, CD24 expression (P=0.025) together with tumour stage (P=0.006) and grade (P=0.011) proved to be independent prognostic parameters." (PMID 12610508, 2003). "First, CD24-positive NSCLCs might be more difficult to culture as cell lines than CD24-negative tumours." (PMID 12610508, 2003).
tumor (continued). "This study establishes CD24 expression as an independent prognostic tumour marker in NSCLC." (PMID 12610508, 2003). "Therefore, the solitary effects of tumor CD24 are undefined." (PMID 41585138, 2026). "Notably, its targeted impact on the CD44+/CD24–population suggests that niclosamide could enhance the sensitivityof CSCs to treatment, thereby preventing tumor recurrence." (PMID 40521512, 2025). "Furthermore, analysis of tumor cells in the GSE149614 dataset revealed that “don't eat me” ligands CD47, CD24, human leukocyte antigen A (HLA‐A), and HLA‐B were significantly upregulated in tumor cells from NUPR1‐high samples, indicating a potential effect of NUPR1+ macrophages on tumor cells." (PMID 40305758, 2025). "Indeed, placing tumor cells in a hypoxic environment promotes CD24 expression through HIFs." (PMID 40486886, 2025). "Therefore, whilst CD24+ sub-populations were only seen in a minority of tumours, they may confer characteristics that are important for metastatic spread." (PMID 40754577, 2025). "Moreover, sialic acid-binding Ig-like lectin 10 (Siglec-10)+ TAMs could promote immune escape through interactions with CD24 signals derived from tumor cells." (PMID 41341850, 2025). "CD24 might play a crucial role in the anti-phagocytic signaling process, as mantle cell lymphoma and chronic lymphocytic leukemia represent a subset of B-cell malignancies with a significantly hostile tumor microenvironment (TME) with M2-like TAMs." (PMID 40770672, 2025). "In addition, the colocalization of IL21-AS1, HIF-1α, and CD24 in necrotic tumour regions further confirmed this hypothesis." (PMID 38702326, 2024). "Importantly, B cells decreased in tumor-bearing mice and increased after CD24-CAR-T cell treatment." (PMID 38242888, 2024). "Additionally, we also found that the expression level of CD24 was lower in tumor tissue (p < 0.05)." (PMID 38773226, 2024). "Interestingly, tumor cells expressing CD24 may promote immune evasion through its interaction with the inhibitory receptor SIGLEC10 expressed by macrophages." (PMID 38358826, 2024). "Finally, we conducted in vivo rescue experiments and found that silencing CD24 in IL21-AS1-overexpressing A2780 cells attenuated the IL21-AS1-mediated increases in tumour volume, weight, and growth rate (n = 7 mice per group in each assay), consistent with the in vitro results." (PMID 38702326, 2024). "Furthermore, it is important to point out that this additional increase in expression correlated with an enhanced tumor growth rate, implying that a supplementary native increase in CD24 expression in exogenously expressing stable cells offered a dose-dependent selective advantage in vivo." (PMID 38214542, 2024). "The growth of tumor cells and the increase of CD24 in the cytoplasm may be related." (PMID 37846296, 2023). "Notably, the high expression of CD24 on the cancer cell surface acts as an innate immune checkpoint molecule that inhibits phagocytosis during the interaction between immune cells and cancer cells, leading to tumor-mediated immune escape." (PMID 37894750, 2023). "Moreover, CD24-Fc may also initiate tumor cell proliferation and behave as a “don’t eat me” signal to assist in tumor evasion from phagocytosis." (PMID 37346042, 2023). "Additionally, CD24 was suggested to be a tumor-initiating cell marker and has been described with additional functions as an adhesion molecule important for invasion and migration, as well as being capable of activating signaling pathways involved in tumor cell proliferation." (PMID 36825029, 2023). "Also, microRNA-34a could reduce the expression of CD24 and Src at the post-transcriptional level, and then regulate the tumor immune escape." (PMID 37359556, 2023).